RET (ret proto-oncogene)
Diseases named in the same sentence as RET in open-access papers (continued):
Sharing a sentence is not in itself a finding about the gene and the disease.
lung cancer (continued). "Few genes are recurrent partners in tyrosine kinase fusions in lung cancer, including CCDC6, a recurrent partner in ROS1 and RET fusions, that can be selected as possible target for new strategies of combined therapy including TKi." (PMID 29455670, 2018). "Our study also highlights that these 70 HKGs maintain low levels of variance across tumour samples when compared to accepted markers of lung cancer (e.g., KRAS, ALK, RET)." (PMID 29761043, 2018). "Given the prevalence of CCDC6 fusion to ROS1 and RET, this analysis will identify and tailor a treatment, with the aim to enhance the TKI efficacy and to prevent resistance in almost 1000 lung cancer patients." (PMID 29455670, 2018). "Nintedanib antagonizes RET and VEGF receptors and blocks endothelial cell proliferation and tumor growth in mouse models of pancreatic and lung cancers." (PMID 30701022, 2018). "We then performed two amplicon-based NGS assays: the Ion AmpliSeq RNA Lung Cancer Research Fusion Panel and the Archer® FusionPlex®ALK, RET, ROS1 v2 kit." (PMID 28970558, 2017). "In the LC2AD lung cancer cell line, the TSC of the CCDC6 gene was physically connected to the PAS of the RET gene; the two genes were separated by more than 3 Mb and located on opposite strands of chromosome 10." (PMID 25034687, 2014). "In conclusion, our results suggest that EGFR, HER2, HER3, and RET are trans-phosphorylated by MET and promote cell proliferation and survival or cell migration as heterodimerisation partners of MET in lung cancer cells with MET amplification." (PMID 21847121, 2011). "With the use of an RTK array, we found that EBC-1 and H1993, two human lung cancer cell lines with MET amplification, exhibited a high level of tyrosine phosphorylation of MET, EGFR, HER2, HER3, and RET under conditions of serum deprivation." (PMID 21847121, 2011). "Surprisingly, RET and PLAT were downregulated by 10- and 2.2-fold in RA-sensitive Calu-6 lung cancer cells, whereas both target genes were upregulated in both neuroblastoma cell lines." (PMID 16012519, 2005). "As RET not typically expressed in lung tissue, RET coverage imbalance has been identified as a reliable marker of fusion presence in lung cancer, as confirmed by previously published studies." (PMID 41373459, 2025). "However, the predominant partner varies depending on the specific type of cancer: in the case of lung cancer, KIF5B accounts for 66–68% of all RET fusions, CCDC6 for 18–22%, and NCOA4 for only 2–3%." (PMID 41373459, 2025). "ALK, ROS1, RET, and NTRK1 fusions are observed frequently in lung cancer." (PMID 40223139, 2025). "Known lung cancer genes (EGFR, KRAS G12C, ALK, MET, RET) were found in 33 patients; 11 had genes relevant to both lung and other cancers (ERBB2, BRAF V600, NTRK), and 37 had genes typically linked to other malignancies (NF1, PIK3CA, PALB2, FGFR2B, FBX7, RAD51)." (PMID 40244261, 2025). "In addition, lung cancers, including the ALK‐positive non‐small‐cell and RET Fusion‐positive variations, constituted about 9% (2/23) of the studies." (PMID 38984669, 2024). "The findings of an electronic search for publications using RET-FISH in lung cancer were compared with the results obtained at the Grenoble University Hospital where 784 EGFR-, KRAS-, ALK-, and ROS1-negative NSCLCs were tested by RET break-apart FISH and confirmed by RNA-sequencing (RNA-seq)." (PMID 39507413, 2024). "Toceranib phosphate is also capable of blocking PDGFR, VEGFR, Flt-3, CSF1R, RET, ALK, and AXL, which may provide potential benefits for dogs with primary lung cancer." (PMID 39902337, 2024). "Out of the 85 publications using RET-FISH analysis, 52 pertained to patients with lung cancer." (PMID 39507413, 2024). "As the most common fusion genes in lung cancer, ALK, RET, and ROS1 were selected for analysis." (PMID 38229122, 2024). "Furthermore, at least 45 RET gene fusion partners have been identified in lung cancer, the most common of which is KIF5B-RET (70 - 90%)." (PMID 39777333, 2024).
lung cancer (continued). "In the past, the treatment plans for advanced lung cancer with RET fusion were similar to those for NSCLC without oncogenes." (PMID 39372206, 2024). "Based on assay design and coverage of key intronic regions of the genome, we were also able to detect a broad range of clinically relevant fusions, such as EML4::ALK, RET, and ROS1 rearrangements with diverse gene partners in lung carcinomas, BRAF::KIAA1549 and EGFRvIII alterations in gliomas." (PMID 39289779, 2024). "In all, 8398 (98%) were adults and 195 (2%) were children; 7865 patients (92%) were treated for lung cancer, of whom 7270 (92%) had an ALK rearrangement, 290 (4%) had an ROS1 rearrangement and 305 (4%) had another molecular abnormality, such as in RET, MET, or NTRK." (PMID 37894307, 2023). "Thus, we conducted a correlation study between FGF11 and EGFR (19DEL, L858R), EGFR (Exon 20ins), KRAS (G12C), ALK, ROS1, BRAF, NTRK1/2/3, MET, and RET, which are all recommended by the NCCN guidelines for the diagnosis of nonsmall cell lung cancer." (PMID 37250453, 2023). "Notably, KRAS, BRAF, ERBB2, PIK3CA, RET, ROS1, ALK, and NRTK1/2/3 have been proposed as prognostic markers, making substantial contributions to genotype-directed therapies for advanced lung cancer." (PMID 36619227, 2023). "Among 23 tissue RET fusion positive patients [20 (lung adenocarcinoma/NSCLC/lung cancer-NOS), 2 (carcinoma of unknown primary), 1 (prostatic adenocarcinoma)] with both tissue and liquid NGS, 14 (61%) patients had RET fusion detected on liquid assay." (PMID 36690680, 2023). "Consistent with our findings, multiple studies have suggested that RET fusions in lung cancer correlate with adenocarcinoma histology, younger age, never smoker status and advanced disease." (PMID 36690680, 2023). "In the pediatric patient population, LIBRETTO-121 (NCT03899792) is a phase 1/2 trial evaluating selpercatinib in patients with advanced solid tumors and primary CNS tumors, not including lung cancer, that harbors a RET alteration." (PMID 37360768, 2023). "None of the 1293 lung carcinomas with driver alterations in EGFR/ALK/ROS1/RET/MET oncogenes had NTRK 5′/3′-end expression imbalances." (PMID 37762506, 2023). "Results of the study carried out at Memorial Sloan Kettering Cancer Center showed that lung cancer patients with RET alterations showed no response to immune checkpoint inhibitors with a median progression-free survival (mPFS) of 3.4 months." (PMID 36358717, 2022). "Similarly, at least 45 RET fusion partners have been identified in lung cancers, with the most common being kinesin family member 5B (KIF5B)-RET (70-90%) and CCDC6-RET (10-25%)." (PMID 35957881, 2022). "Besides the sensitive detection of SNVs and INDELs, gene fusions in ALK, RET, or ROS1 were detected in 2.9% of ctDNA-positive lung cancer cases, exemplifying the clinical applicability of an amplicon-based assay for the detection of novel fusions." (PMID 35486650, 2022). "RET fusions were recently identified in lung cancer and to date several phase II trials have investigated the role of RET non-selective multi-kinase inhibitors in RET+ lung cancer patients, with unsatisfactory clinical results." (PMID 34503226, 2021). "These targetable RTK rearrangements consist of ALK fusion in lung cancer and anaplastic large cell lymphoma, ROS1 fusion in lung cancer and glioblastoma, RET fusion in lung and thyroid cancer, FGFR fusion in bile duct and urothelial carcinoma, as well as NTRK fusion in pan-cancer." (PMID 34650924, 2021). "Among which, RASGEF1A-RET26 was previously identified in breast cancer as a tumorigenic fusion sensitive to RET inhibitors, but not previously reported in lung cancer." (PMID 34508169, 2021). "Radiosensitiziation could also be induced in a lung cancer model by vandetanib, an inhibitor of VEGFR2 and EGFR but also of RET and other receptors." (PMID 32903756, 2020).
lung cancer (continued). "There is no comprehensive study of the efficacy of any RET inhibitor in preclinical lung cancer models with RET fusions." (PMID 33318047, 2020). "Owing to a lack of preclinical models of lung cancer with RET rearrangements there have been very few studies examining the efficacy of RET inhibitors and signaling pathways exploited by RET fusions to drive tumorigenesis prior to clinical trials." (PMID 33318047, 2020). "In contrast, the activity of immunotherapy in RET-rearranged lung cancers has not been well characterized." (PMID 31192313, 2019). "We therefore examined RET expression at the C-terminus in 37 lung cancer cell lines with or without RET fusion." (PMID 30943926, 2019). "The first results of RET-driven NSCLC patients were reported at the American Society of Clinical Oncology Annual 2018 meeting and updated at the 19th IASLC World Conference of Lung Cancer." (PMID 35582269, 2019). "We demonstrated that the transcription levels of ALK- or RET-fusion partner genes, such as EML4, CCDC6 and KIF5B, were constitutively activated in lung cancer cells, and the expression at the C-terminal region of ALK, RET, or ROS1 was also markedly elevated in each fusion-positive lung cancer cell." (PMID 30943926, 2019). "Furthermore, the lung cancer cell line Lc2/ad, which carries a RET fusion, shows more resistance to erlotinib compared to SW48 cells, and direct targeting of RET inhibition in Lc2/ad cells can be bypassed by EGFR activation." (PMID 31653970, 2019). "Modeling of amplification by overexpression of wild-type RET sequence validates that RET overexpression, similar to RET fusions, can lead to aberrant downstream signaling like other RTKs such as ERBB2 amplification in breast cancer or MET amplification in lung cancer." (PMID 30446652, 2018). "In addition, a single-tube multiplexed method, namely a combination of fusion-specific and 3′overexpression detection strategy, have detected ROS1, RET, and ALK fusions in lung cancer." (PMID 28915704, 2017). "The Archer® FusionPlex®ALK, RET, ROS1 v2 allowed the expected detection of the fusion breakpoints present in the samples: EML4-ALK (E6:A20) and CCDC6-RET (C1:R12) for the commercialized sample, and EML4-ALK (E6:A20) for the human lung cancer cell line H2228." (PMID 28970558, 2017). "As a class III/V multikinase inhibitor, Sunitinib was reported to suppress various kinds of tumors, such as human metastatic renal cell carcinoma, lung carcinoma, glioblastoma, melanoma by inhibiting the activation of VEGFR-1, 2 and 3, PDGFR-α, β, Kit, Flt3 and RET." (PMID 29152075, 2017). "In the current study, we have explored the mutational spectrum of 26 well-established cancer-related genes and ALK, RET, and ROS1 gene fusions by massive parallel sequencing in a large panel of thoroughly histopathologically classified primary LC and LCNEC lung cancers." (PMID 26124082, 2015). "The requirement for co-development and co-approval of CDx in order to get TKIs approved against these RTK (ROS1, RET, NTRK1, AXL, PDGFR-α) rearrangement lung cancer represents the daunting challenge to successfully translate decades of basic science research into benefit of cancer patients." (PMID 24744988, 2014). "Whilst not validated, oncogenic RET rearrangements and fusions are common in thyroid and lung cancer, and the presence of infrequent activating fusions in HGG do not seem unlikely." (PMID 24548782, 2014). "The RET/β actin mRNA levels were not significantly different between lung cancer (6.359 ± 15.268) and adjacent normal lung tissues (8.205 ± 28.931, P = 0.6332; n = 157)." (PMID 23342255, 2012). "The RET/β actin mRNA levels were not significantly different between lung cancer (6.359 ± 15.268) and adjacent normal lung tissues (8.205 ± 28.931, P = 0.6332)." (PMID 23342255, 2012).
lung cancer (continued). "In the present study, we demonstrated that XB130 is involved in proliferation and survival of WRO thyroid cancer cells (with RET/PTC mutation) and A549 lung carcinoma cells (without RET/PTC mutation)." (PMID 22928011, 2012). "Together, these results suggested that MET, EGFR, HER2, and HER3 activate AKT and ERK signalling pathways and promote cell proliferation and survival in lung cancer cells with MET amplification, whereas MET, HER2, and RET activate the STAT3 signalling pathway and promote cell migration." (PMID 21847121, 2011). "In this scenario, customized medicine has brought successful outcomes in drug selection for lung cancer patients with NSCLC based on the paradigms of their molecular profiles, specifically those with positive genetic alterations in EGFR, ALK, ROS-1, HER2, BRAF, MET, and RET genes." (PMID 39410578, 2024). "However, it will not be pragmatically feasible to perform phase Ib/II clinical trials of discrete combination regimens for each individual therapy-resistant, rare molecular subset of lung cancer (e.g., ROS1-, RET-, and NTRK1-3-rearranged NSCLC) and for each distinct genomic mechanism of resistance." (PMID 37923925, 2023). "Variant-specific PCR was performed for 744 tumors with a normal 5′/3′-end expression ratio: there were no rearrangements in 172 EGFR/ALK/ROS1/RET/MET-negative lung cancers and 125 pediatric tumors, while NTRK3 fusions were detected in 2/447 (0.5%) non-lung adult malignancies." (PMID 37762506, 2023). "Similarly, KIF5B::RET fusions represent more than 70% of RET alterations in lung cancers; however, none of the RET-rearranged microsatellite-unstable tumors carried this variant." (PMID 37686416, 2023). "RET fusion may be responsible for the pathogenesis in patients with lung cancer without mutations in EGFR, ALK, or ROS1, which may be related to the RET-induced promotion of apoptosis resistance." (PMID 35211155, 2022). "In addition, fusions in ALK (overall, Fisher’s exact test P < 0.0001; lung cancer, P < 0.0001), ROS1 (overall, Fisher’s exact test P < 0.0001; lung cancer, P < 0.0001) and RET (overall, Fisher’s exact test P = 0.006; lung cancer, P < 0.0001) were associated with an earlier disease onset." (PMID 36369474, 2022). "The Ion AmpliSeq RNA Lung Cancer Research Fusion Panel is based on an amplicon target enrichment approach that allows amplification and detection of 70 known fusion transcripts for the ALK, RET, ROS1, and NTRK1 genes using a couple of primers specific of each fusion." (PMID 28970558, 2017). "Our results show that vandetanib can effectively inhibit Calu-6 cell invasion, indicating that RET may not be required for lung cancer formation but is necessary for tumor progression." (PMID 25720956, 2015). "First, activation of RET through amplification or low copy number gain might not represent a driver molecular alteration in lung cancer." (PMID 25884512, 2015). "Given that patients with c-RET fusions do not harbor mutations or fusions in EGFR, KRAS or ALK oncogenes, it is likely that c-RET fusion genes represent lung adenocarcinoma drivers and will lead to the definition of a new subclass of lung cancer." (PMID 23405175, 2013). "Our data suggest that heterodimers of MET with EGFR, HER2, HER3, or RET have differential roles in tumour development, and they provide new insight into the function of trans-phosphorylated RTKs as heterodimerisation partners of MET in lung cancer with MET amplification." (PMID 21847121, 2011).
lung cancer (continued). "Non–small cell lung cancer harboring a SMARCA4/SMARCA2 deficiency has no established treatment because it is mutually exclusive to genetic abnormalities such as EGFR mutations and anaplastic lymphoma kinase (ALK) and RET fusions, for which there are established treatments." (PMID 39625239, 2025). "Unique genomic characteristics of human never-smoker lung cancer include somatic activating point mutations or fusions affecting EGFR (45%), anaplastic lymphoma kinase (ALK; 5–11%), ROS (1.5–6%), human epidermal growth factor receptor 2 (HER2; 3–5%) and rearranged during transfection (RET; 2%)." (PMID 39902337, 2024). "However, anti-tumor activity of Apatinib in RET-rearranged lung cancer has never been reported." (PMID 27494860, 2016). "Of these fusions, 16 (including ALK, ARAF, BRAF, FGFR1, FGFR3, RET, and ROS1) and 21 (including ABL1, GNAS, JAK2, and NRG1) were classified as either related to lung cancer, or as oncogenes that have not been reported in lung cancer, respectively." (PMID 36153311, 2022). "Cancers such as lung cancer, head and neck cancer, and melanoma have exhibited clinical benefit with IO, although patients who are never smokers (i.e., ALK, ROS, and RET) or whose tumors express mutant EGFR showed 0–14% response rates, irrespective of PD-L1 expression levels." (PMID 34001994, 2021). "“Non-KRAS oncogene-driven lung cancer subtypes (e.g., ROS1, MET, BRAF, HER2, RET) is less well-studied, however, most of these other non-KRAS molecular subtypes (possibly apart from BRAF V600 mutation and MET gene alteration) are associated with a light-to-never smoking history." (PMID 34575691, 2021). "Although RET protein overexpression was not perfectly matched with the RET rearrangements, FISH analysis might be one of the candidate method for detecting RET gene status in lung cancer." (PMID 23342255, 2012).